BDKRB1 (bradykinin receptor B1)
Description:
This is a receptor for bradykinin. Could be a factor in chronic pain and inflammation.
Synonyms: B1R; BRADYB1; BKR1; B1BKR; BKB1R
Tractability: Small molecule: a drug acting on it is in phase 2 or 3 trials; a high-quality ligand is known; it belongs to a druggable protein family. Antibody: UniProt places it where antibodies can reach, with high confidence; its Gene Ontology location is reachable by antibodies, with high confidence; UniProt predicts a signal peptide or a membrane-spanning region. PROTAC: a small molecule that binds it is known.
Target class: Family A G protein-coupled receptor; Short peptide receptor (family A GPCR); Bradykinin receptor; Membrane receptor; Peptide receptor (family A GPCR)
Chemical probes: BI 113823 (high quality), CHEMBL2087421
Gene: Protein-coding gene on chromosome 14 (96,256,182 to 96,268,967, forward strand). Ensembl gene ENSG00000100739.
Subcellular location: Cell membrane
Pathways (Reactome):
Signal Transduction: G alpha (i) signalling events; G alpha (q) signalling events; Peptide ligand-binding receptors
Gene Ontology:
Molecular function: bradykinin receptor activity; protein binding; G protein-coupled receptor activity; peptide binding
Biological process: G protein-coupled receptor signaling pathway; positive regulation of cytosolic calcium ion concentration; cell migration; inflammatory response; negative regulation of blood pressure; negative regulation of cell growth; positive regulation of leukocyte migration; positive regulation of release of sequestered calcium ion into cytosol; response to lipopolysaccharide; response to mechanical stimulus
Cellular component: endoplasmic reticulum; plasma membrane; membrane
Genetic constraint (gnomAD): Loss-of-function variants: 1 observed, 1.38 expected, observed/expected ratio (o/e) 0.72, 90% interval 0.22 to 1.85. That is too few expected variants to judge how well the gene tolerates losing a copy. Missense variants: 414 observed, 463.5 expected, observed/expected ratio (o/e) 0.89, 90% interval 0.82 to 0.97. Synonymous variants: 192 observed, 199.75 expected, observed/expected ratio (o/e) 0.96, 90% interval 0.85 to 1.08.
Homologues: Orthologues: rabbit BDKRB1 (77% identical), dog BDKRB1 (75% identical), chimpanzee BDKRB1 (74% identical), mouse Bdkrb1 (68% identical), rat Bdkrb1 (67% identical), zebrafish bdkrb1 (36% identical), Caenorhabditis elegans npr-17 (20% identical). Paralogues in human: BDKRB2 (35% identical), AGTR1 (28% identical), AGTR2 (27% identical), APLNR (25% identical), RXFP4 (24% identical), GPR25 (24% identical), GPR15 (22% identical).
Diseases named in the same sentence as BDKRB1 in open-access papers:
BDKRB1 is named in the same sentence as 161 diseases in open-access papers, as found by Europe PMC text mining. Sharing a sentence is not in itself a finding about the gene and the disease. The quoted sentences say what the papers report.
diabetes (20 papers, 2009 to 2022). "Studies have shown BDKRB1 activation and/or increased expression in several pathological states, including infection, allergy, arthritis, cancer, chronic pain and inflammation, diabetes mellitus, and neurological disorders, such as epilepsy, stroke, multiple sclerosis, and Alzheimer's disease." (PMID 27293319, 2016).
COVID-19 (17 papers, 2020 to 2025). A disease caused by infection with severe acute respiratory syndrome coronavirus 2. "ACE2 depletion would likely block the inactivation of these two kinins, which would then be free to activate the endothelial bradykinin receptor B1 (B1R) and promote edema, inflammation, and oxidative stress in COVID-19." (PMID 33375371, 2020). "In addition, BK1-8 main receptor, BDKRB1, mRNA expression were upregulated in circulating cells from patients with COVID-19." (PMID 35812405, 2022). "Follow-up analysis indicated that CXCR3-aab, AGTR1-aab, MAS1-aab, CHRM5-aab, and BDKRB1-aab were the five most significant predictors of COVID-19 disease-severity classification based on the number of nodes and the Gini decrease criteria for measuring variable importance." (PMID 35264564, 2022). "In this context, autoantibodies such as ACE2-aab, AGTR2-aab, BDKRB1-aab, CXCR3-aab, MAS1-aab, CHRM5-aab, NRP1-aab, F2R-aab, STAB1-aab appeared to play a major role in stratifying COVID-19 by disease burden." (PMID 35264564, 2022). "In summary, CoVex identifies the protein BDKRB1, which appears to play a role in SARS-CoV-2 host cell entry and can be targeted by several ACE inhibitors widely used in clinical trials to treat COVID-19." (PMID 32665542, 2020). "Interestingly AABs to the vaso- and immunoregulatory receptors CXCR3, CHRM5, BDKRB1, MAS1, AGTR1, F2R/PAR-1, and STAB1 were the most significant classifiers of acute COVID-19 severity in our recent study." (PMID 36238301, 2022).
breast cancer (11 papers, 2011 to 2024). A primary or metastatic malignant neoplasm involving the breast. "In addition, crosstalk between BDKRB1 and EGFR has been shown to maintain tumor growth in the breast cancer." (PMID 27484806, 2016).
glioblastoma (11 papers, 2012 to 2025). The most malignant astrocytic tumor (WHO grade IV). "Treatment of human U87 MG glioblastoma cells with 100 nM bradykinin for 12 and 24 h led to significant 37% and 45% augmentations in levels of the BDKRB1 protein." (PMID 32182968, 2020). "Nevertheless, suppressing translation of the BDKRB1 gene using RNAi concurrently decreased the bradykinin-triggered invasion by human malignant U87 MG glioblastoma cells." (PMID 32182968, 2020). "Compared to untreated glioblastoma cells, exposure to 100 nM bradykinin for 12 and 24 h increased levels of BDKRB1 (lanes 3 and 4)." (PMID 32182968, 2020). "This study further demonstrated that the bradykinin-BDKRB1/2 axis takes part in the rapid migration and invasion of glioblastoma cells due to induction of aqp4 gene expression." (PMID 32182968, 2020). "In this study, we showed the effects of bradykinin on elevation of BDKRB1 in human glioblastoma cells." (PMID 32182968, 2020). "Expressions of AQP4 and BDKRB1/2 mRNAs in human glioblastoma were mined in The Cancer Genome Atlas (TCGA)." (PMID 32182968, 2020). "This study showed that the bradykinin-BDKRB1/2 axis contributes to migration and invasion of malignant glioblastoma cells through regulation of aqp4 gene expression." (PMID 32182968, 2020). "The present study showed overexpression of AQP4 in human glioblastomas and involvement of the bradykinin-BDKRB1 axis in regulating expression of this channel gene." (PMID 32182968, 2020). "The present study further showed the roles of the BDKRB1/2-MAPK-NF-κB axis in the tumorigenesis of glioblastomas." (PMID 32182968, 2020). "Bradykinin specifically elevated levels of BDKRB1 in human glioblastoma cells and stimulated an influx of Ca2+." (PMID 32182968, 2020). "In this study, we investigated the roles of the bradykinin-BDKRB1/B2 axis in regulating glioblastoma cell activities and the possible mechanisms from the viewpoint of calcium influx-induced signal-transducing events in glioblastomas." (PMID 32182968, 2020). "The bradykinin-BDKRB1 axis is involved in regulating the aqp4 gene in glioblastoma cells via activating the MAPK-NF-κB mechanism." (PMID 32182968, 2020). "BDKRB1 contributes to interleukin-8 production and glioblastoma migration." (PMID 36785669, 2023). "In human U87 MG glioblastoma cells, silencing BDKRB1 reduced tumor migration and invasion." (PMID 36290882, 2022). "Bradykinin can trigger BDKRB1/2 and then stimulate Ca2+ influx in glioblastoma cells." (PMID 32182968, 2020). "Furthermore, exposure of human U87 MG glioblastoma cells to bradykinin specifically increased levels of BDKRB1." (PMID 32182968, 2020). "Thus, this study demonstrated the contribution of the bradykinin-BDKRB1 axis to migration and invasion of human and murine glioblastoma cells." (PMID 32182968, 2020). "In human glioblastomas and normal brain tissues, basal levels of BDKRB1/2 mRNA were detected." (PMID 32182968, 2020). "The bradykinin-BDKRB1 axis participates in migration and invasion of glioblastoma cells." (PMID 32182968, 2020). "The bradykinin-BDKRB1 axis may be a target for therapy of glioblastomas." (PMID 32182968, 2020). "Also, we demonstrated the existence of BDKRB1/2 proteins in human malignant glioblastoma cells." (PMID 32182968, 2020). "As a result, the bradykinin-BDKRB1/2 axis contributes to regulation of AQP4 expression as well as migration and invasion of glioblastoma cells." (PMID 32182968, 2020). "Fascinatingly, bradykinin can bind and activate bradykinin receptor B1 and B2 (BDKRB1/2) to regulate the permeability of the blood-tumor barrier in glioblastomas." (PMID 32182968, 2020). "As a result, the bradykinin-BDKRB1 axis-induced AQP4 plays an important role in the migration and invasion of glioblastoma cells." (PMID 32182968, 2020). "Levels of BDKRB1 and BDKRB2 were detected in human U87 MG glioblastoma cells (top two panels, lane 1)." (PMID 32182968, 2020).
glioblastoma (continued). "Application of BDKRB1 siRNA to human glioblastoma cells did not affect the wound-healing activity." (PMID 32182968, 2020).
glioma (10 papers, 2012 to 2025). A benign or malignant brain and spinal cord tumor that arises from glial cells (astrocytes, oligodendrocytes, ependymal cells). "The expression level of BDKRB1 gradually increases with higher WHO grades of glioma, suggesting that it may serve as a risk factor for patients." (PMID 41331166, 2025). "In patients with G4 grade glioma, the copy number of BDKRB1 mRNA copies/μg RNA (Me = 890.10 copies/μg RNA) was significantly higher (p = 0.020) compared to the mRNA BDKRB1 level in patients with G2 grade (Me = 425.13 copies/μg RNA)." (PMID 38254732, 2024). "Our results suggest that the assessment of mRNA BDKRB1, PRKAR1A, MAP2K2, and EGFR by RT-qPCR in samples of patients with gliomas may have diagnostic significance." (PMID 38254732, 2024). "The aim of this study was to determine the expression of BDKRB1 and BDKRB2 genes and the levels of B1R and B2R proteins in human gliomas, with consideration of the degree of malignancy." (PMID 38254732, 2024). "The aim of the present study was to ascertain the expression of BDKRB1 and BDKRB2 genes, as well as the level of B1R and B2R proteins in human gliomas, depending on the degree of malignancy." (PMID 38254732, 2024).
Alzheimer disease (9 papers, 2013 to 2025). A progressive, neurodegenerative disease characterized by loss of function and death of nerve cells in several areas of the brain leading to loss of cognitive function such as memory and language. "In Alzheimer's disease, which appears early in DS individuals, BDKRB1 activation likely contributes to neuroinflammation." (PMID 27293319, 2016).
multiple sclerosis (7 papers, 2016 to 2024). A progressive autoimmune disorder affecting the central nervous system resulting in demyelination. "Genetic disruption of the bradykinin receptors B1 (BDKRB1) and B2 (BDKRB2) decreases inflammatory sensitivity in a variety of disease‐specific models, including the multiple sclerosis model experimental autoimmune encephalomyelitides and a gout model induced by monosodium urate injection." (PMID 35760453, 2022).
colitis (4 papers, 2015 to 2025). Inflammation of the colon. "Colitis caused strong induction of colonic kininogen 2 transcription and bradykinin receptor B1‐positive cells in the disrupted mucosa." (PMID 40018982, 2025).
astrocytoma (3 papers, 2010 to 2022). "Transcripts exhibiting significant under expression in trisomic BG01V APCs and CCF-STTG1 astrocytoma cells relative to diploid H9 APCs include several markers of normal differentiated astrocytes, including TRPA1, GABRA2, BDNF, BDKRB1 and BDKRB2." (PMID 20423517, 2010).
brain tumors (3 papers, 2012 to 2024). "Remarkably, knocking-down BDKRB1 concurrently attenuated bradykinin-induced migration and invasion of brain tumor cells." (PMID 32182968, 2020). "Quantitative assessment of mRNA BDKRB1, PRKAR1A, MAP2K, and EGFR in patients with brain tumors may hold diagnostic and therapeutic significance." (PMID 38254732, 2024). "Knocking-down BDKRB1 simultaneously inhibited AQP4 expression and migration and invasion by human brain tumor cells." (PMID 32182968, 2020).
epilepsy (3 papers, 2016 to 2025). A brain disorder characterized by episodes of abnormally increased neuronal discharge resulting in transient episodes of sensory or motor neurological dysfunction, or psychic dysfunction. "The disparity in the transcriptional activity of BDKRB1 and BDKRB2 may be explained by the “cross-talk” between B2R and B1R, as previously demonstrated in a rat model of kindling-induced epilepsy." (PMID 38254732, 2024).
neuropathy (3 papers, 2010 to 2022). A disorder affecting the nervous system that manifests with pain, tingling, numbness, and/or muscle weakness. "The analysis of over-represented diseases and mesh diseases generated by Genomatix reveal role of Bdkrb1 in inflammatory pain, neuropathy, and chronic inflammation and CNS disorder." (PMID 31417109, 2019). "Taken together, these results lend credence to the possibility that BDKRB1 plays a role in the development of neuropathy and indicate that selective B1 receptor antagonists may hold broad therapeutic potential in the management of chronic pain." (PMID 35760453, 2022).
Anxiety (2 papers, 2019 to 2023). Intense feelings of nervousness, tension, or panic often arise in response to interpersonal stresses. "Our finding that especially BDKRB2 levels were altered after acute and chronic stress, major risk factors for anxiety disorders, encouraged us to test whether antagonists of BDKRB1 or BDKRB2 affect anxiety-like behaviour in mice." (PMID 31857655, 2019). "Since acute or chronic stress did not affect gene or protein expression of BDKRB1, nor did the BDKRB1 receptor antagonist influence anxiety-like behaviour, we concentrated on the BDKRB2." (PMID 31857655, 2019). "Furthermore, we tested the effect of BDKRB1 and BDKRB2 antagonists on mouse anxiety-like behaviour and physiological stress responses." (PMID 31857655, 2019).
brain glioma (2 papers, 2022 to 2024). A malignant glioma that involves the brain. "Increased expression of kinin receptors BDKRB1 and BDKRB2 in brain gliomas, depending on the degree of malignancy, suggests the involvement of kinins and their receptors in the disease’s pathogenesis." (PMID 38254732, 2024).
experimental autoimmune encephalomyelitis (2 papers, 2017 to 2023). An autoimmune demyelinating disease of the central nervous system that is produced experimentally in animals by the injection of homogenized brain or spinal cord in Freund's adjuvant. "The BDKRB1 agonist markedly reduces clinical symptoms of experimental autoimmune encephalomyelitis in mice, whereas its antagonist leads to accelerated disease onset and greater severity of the disease." (PMID 28912500, 2017).
Hepatic fibrosis (2 papers, 2021 to 2022). The presence of excessive fibrous connective tissue in the liver. "This development among Kng1, Bdkrb1, and Bdkrb2 gene expressions, and myofibroblast activators and chronic liver injury creates a new direction in the study of liver fibrosis and its resolution." (PMID 34566641, 2021).
lung fibrosis (2 papers, 2023 to 2024). "Studies have demonstrated that the deletion of BDKRB1 in mice inhibits fibrosis, suggesting the receptor’s role in promoting fibrosis and its potential significance in mammalian lung fibrosis." (PMID 38575860, 2024).
ovarian carcinoma (2 papers, 2023 to 2026). A malignant neoplasm originating from the surface ovarian epithelium. "One hub gene, BDKRB1, is a well-established tumor suppressor gene, which is frequently mutated in familial breast and ovarian cancers." (PMID 36785669, 2023).
ulcerative colitis (2 papers, 2022 to 2025). An inflammatory bowel disease involving the mucosal surface of the large intestine and rectum. "In the ulcerative colitis single‐cell dataset, we found that BDKRB1 expression was significantly increased in UC and was mainly expressed in the pro‐inflammatory fibroblast subpopulation." (PMID 40859429, 2025). "We also performed a correlation analysis based on the immunohistochemical score of BDKRB1 in ulcerative colitis and the Mayo score of the corresponding patients." (PMID 40859429, 2025). "The results showed that the IHC score of BDKRB1 was significantly positively correlated with the Mayo score of ulcerative colitis." (PMID 40859429, 2025).
anxiety disorder (1 paper, 2019). A category of psychiatric disorders which are characterized by anxious feelings or fear often accompanied by physical symptoms associated with anxiety. "Of the 21 analysed KNG1 SNPs, 17 BDKRB1 SNPs, and 20 BDKRB2 SNPs, 5, 8, and 1 associated with anxiety disorders at the nominal p < 0.05 level, respectively." (PMID 31857655, 2019). "In human genetic association analysis, variants in genes for the bradykinin precursor (KNG1) and the bradykinin receptors (BDKRB1 and BDKRB2) were associated with anxiety disorders (p < 0.05)." (PMID 31857655, 2019). "Therefore, we systematically selected a comprehensive set of SNPs from the KNG1, BDKRB1, and BDKRB2 genes and genotyped them in a well-characterized Finnish anxiety disorder case-control sample, representative of the Finnish population." (PMID 31857655, 2019). "To investigate whether genetic variants in the KKS genes associate with anxiety disorders, we genotyped SNPs from KNG1, BDKRB1, and BDKRB2 in anxiety disorder cases (n = 321) and carefully matched controls (n = 653) from the Finnish population-based Health 2000 Survey." (PMID 31857655, 2019).
candidiasis (1 paper, 2016). Infection with the organism Candida. "Moreover, the relative contributions of Bdkrb1 and Bdkrb2 in renal defense against candidiasis need to be determined, which is possible with specific knockout mouse strains." (PMID 27814401, 2016).
colorectal adenoma (1 paper, 2025). An adenoma that arises from the colon or rectum. "Therefore, we verified the co‐localization of BDKRB1 and ADAMDEC1 in pathological sections of patients with colorectal adenoma." (PMID 40859429, 2025).
injury (1 paper, 2011). Damage inflicted on the body as the direct or indirect result of an external force, with or without disruption of structural continuity. "As previously shown, depletion or pharmacological blockade of the bradykinin receptor B1 (B1R), but not B2R, attenuated postischemic inflammation and blood-brain-barrier damage both after transient middle cerebral artery occlusion or traumatic brain injury in mice." (PMID 21457546, 2011).
papillary renal cell carcinoma (1 paper, 2023). A rare subtype of renal cell carcinoma, arising from the renal tubular epithelium and showing a papillary growth pattern, which typically manifests with hematuria, flank pain, palpable abdominal mass or nonspecific symptoms, such as fatigue, weight loss or fever. "BDKRB1, NMUR2, PMCH, and SAA1 may contribute to the occurrence and development of papillary renal cell carcinoma." (PMID 36785669, 2023).
stomatitis (1 paper, 2024). Inflammation of the oral mucosa due to local or systemic factors. "Furthermore, we analyzed the expression of Tnf-α and Il-6 mRNA as the inflammation-related genes and Cox-2 and Bdkrb1 mRNA as the pain-related genes in wound tissue through qPCR to determine whether EA suppresses stomatitis pain." (PMID 39570913, 2024). "However, in this study, Bdkrb1 mRNA expression levels were not significantly higher in the stomatitis/PS group than in the healthy group; therefore, we could not confirm the effect of EA on Bdkrb1." (PMID 39570913, 2024).